ORAI2 (ORAI calcium release-activated calcium modulator 2)
Diseases named in the same sentence as ORAI2 in open-access papers (continued):
Sharing a sentence is not in itself a finding about the gene and the disease.
cancer (10 papers, 2015 to 2024). A tumor composed of atypical neoplastic, often pleomorphic cells that invade other tissues. "In the presence of TRPV6, different cancer cell lines decrease the expression of Orai2, a calcium channel participating in SOCE." (PMID 37576552, 2023). "In cancer cells, Orai1 and Orai2 expression is upregulated and modulates cell migration by regulation of the AKT/mTOR/NF-κB signaling pathway." (PMID 34768857, 2021). "According to these data, Orai2 upregulation in cancer cells was greater than that of Orai1 (1.2 vs. 1.7 for Orai1 and Orai2, respectively)." (PMID 35008277, 2021). "Specifically, the dysregulation of distinct molecular components of SOCE, especially the STIM1 and Orai1 proteins and their homologues STIM2, Orai2, and Orai3, plays important roles in the pathophysiology of different types of cancer." (PMID 29951353, 2017). "Despite the generally low PSI values for the 325 cryptic 3’SSs from the CLL-only analysis, we identified four genes previously implicated in cancer (TTI1, MAP3K7, FXYD5, PFDN5) and six others (YIF1A, ORAI2, ZNF91, ZNF548, RP11–1280I22." (PMID 25768983, 2015). "The oncogenic role of Orai2 has been demonstrated in various human cancers including OSCC." (PMID 37759448, 2023). "In addition to their implication in different physiological processes, Orai2 and Orai3 are also involved in a variety of pathophysiological events, including cancer." (PMID 35008277, 2021). "Based on numerous previous studies, Orai channels (Orai1, Orai2 and Orai3 channels) control Ca2+ release-activated Ca2+ (CRAC) currents and contribute to SOCE currents in other types of cells, including various cancer cells." (PMID 37759164, 2023). "In the human colorectal cancer cell line HT29, the expression of Orai3, as well as Orai1, Orai2, STIM1, and TRPC1 has been shown to be enhanced as compared to the normal human colon mucosal epithelial cell line NCM460, whereas STIM2 expression was downregulated in cancer cells." (PMID 34768857, 2021). "Via The Cancer Genome Atlas (TCGA), French, Sun, and Gene Expression Omnibus (GEO) (GDS3885) datasets, we collected 1231 cases with RNA-seq data and analyzed the functional annotation of Orai2 by gene ontology (GO) and Kyoto Encyclopedia of Genes and Genomes (KEGG) pathway analysis." (PMID 31772693, 2019).
tumor (6 papers, 2018 to 2024). "In contrast, in T47D the expression of Orai2 was found to be significantly lower than that in non-tumor MCF10A (p < 0.05)." (PMID 35008277, 2021). "Orai2 was not investigated as it does not mediate Ca2+ entry in tumor cells, whereas it underlies SOCE in mouse brain neurons and endothelial cells and in mouse T cells." (PMID 30123430, 2018). "Moreover, the expression of TRPC1, ORAI1, ORAI2, ORAI3 and STIM1 was increased in tumor cells in contrary to STIM2 protein which was found to be depleted." (PMID 31010205, 2019). "We found that the mRNA levels of Orai2 were higher in GBM than in nonneoplastic brain tissues, indicating that Orai2 acted as a tumor promoter in GBM." (PMID 31772693, 2019).
infection (3 papers, 2013 to 2021). The state of being infected such as from the introduction of a foreign agent such as serum, vaccine, antigenic substance or organism. "Knockdown of Orai3 transcripts however required the use of a multiplicity of infection (moi) of adenovirus (moi 250), significantly higher than that required to achieve knockdown of Orai1 and Orai2 transcripts (moi 100)." (PMID 24040356, 2013).
ORAI2 also shares sentences with these, for which no sentence is quoted: acute myeloid leukemia (3 papers); Cerebral Artery (1); cognitive decline (1); diffuse large B-cell lymphoma (1); esophageal tumor (1); graft versus host disease (1); inflammatory bowel disease (1); kidney diseases (1); kidney nephropathy (1); Lymphadenopathy (1); oligoastrocytoma (1); oligodendroglioma (1); parathyroid adenoma (1); pheochromocytoma and paraganglioma (1); preeclampsia (1); Splenomegaly (1); Stroke (1); thyroid carcinoma (1); viral infection (1).